YY1 (YY1 transcription factor)
Diseases named in the same sentence as YY1 in open-access papers (continued):
Sharing a sentence is not in itself a finding about the gene and the disease.
lung fibrosis (10 papers, 2015 to 2026). "Our findings identify YY1/FTL-mediated ferroptosis as a key mechanism by which PS-NPs induce pulmonary fibrosis." (PMID 41560817, 2026). "Our in vivo data also indicated that delivery of an adenovirus-mediated Yy1 shRNA vector under the control of the surfactant protein C promoter protected mice from PS-NPs-induced pulmonary fibrosis." (PMID 41560817, 2026). "YY1 nuclear translocation promotes diabetic nephropathy-induced renal fibrosis, and YY1 is involved in cancer and pulmonary fibrosis." (PMID 41170186, 2025). "YY1 can promote fibrosis under certain conditions, such as diabetic nephropathy and pulmonary fibrosis." (PMID 41170186, 2025). "A previous study suggested that FOXL1 and YY1 regulate multiple functional aspects of lung fibroblasts as a key transcription factor and are involved in idiopathic pulmonary fibrosis pathogenesis." (PMID 37925496, 2023). "Our previous work has demonstrated the regulation of YY1 in idiopathic pulmonary fibrosis and pathogenesis of fibroid lung." (PMID 31703732, 2019). "YY1 is overexpressed in fibroblasts in both human pulmonary fibrosis and murine fibrotic models, regulating fibrogenesis at least in part by increasing α-sma and collagen expression." (PMID 31703732, 2019). "Here we found that YY1 in lung epithelial cells plays an important role in pathogenesis of lung fibrosis." (PMID 31703732, 2019). "Targeted inhibition of YY1 alone or combined with TGF-β or NF-κB inhibitors to treat pulmonary fibrosis will provide encouragement for further evaluation." (PMID 31703732, 2019). "We and others have shown that IL-13-induced lung fibrosis is associated with activation of AKT and YY1 signaling." (PMID 25775215, 2015). "Together, these findings show that AT2 cell specific YY1 knockdown re-establishes antioxidant and iron homeostasis, limits GPX4-dependent ferroptosis, and markedly attenuates PS-NPs-induced pulmonary fibrosis, supporting YY1 as a potential therapeutic target in nanoplastic-related lung injury." (PMID 41560817, 2026). "Notably, YY1 is also persistently up-regulated in classical bleomycin-induced models of pulmonary fibrosis and has been shown to promote fibroblast α-SMA expression and collagen deposition." (PMID 41560817, 2026). "However, the specific function of YY1 in lung epithelial cells during the pathogenesis of lung fibrosis is yet to be determined." (PMID 31703732, 2019). "However, the specific function of YY1 in AECs during the pathogenesis of pulmonary fibrosis is yet to be determined." (PMID 31703732, 2019). "In view of the different Th1/Th2 immune response between the two mouse lines, whether the different levels of YY1 in primary fibroblast cells are related with Th1/Th2 response and pulmonary fibrosis remain to be determined." (PMID 31703732, 2019). "In addition, YY1 can directly upregulate α-SMA and collagen expression, and YY1 knockdown protects against lung fibrosis by decreasing collagen and α-SMA." (PMID 25775215, 2015). "Moreover, in fibroblasts and idiopathic pulmonary fibrosis models, YY1 is regulated post-translationally by the E3 ubiquitin ligase NEDD4, which ubiquitinates YY1, alters its protein stability, and thereby modulates TAB1-dependent profibrotic proliferation and extracellular matrix production." (PMID 41560817, 2026). "However, the specific function of YY1 in epithelial cells during the pathogenesis of pulmonary fibrosis remains unknown." (PMID 31703732, 2019). "Therefore, we hypothesize that IL-13 induces lung fibrosis by activation of YY1 through an AKT pathway." (PMID 25775215, 2015). "Among them is the zinc-finger transcription factor, Yin and Yang (YY1), which has been shown to play a critical role in lung epithelial cell development and TGF-beta-induced lung fibrosis." (PMID 33290721, 2020). "To further verify the implications of the YY1/HSF1/miR-214/THY1 axis in IPF development, we used bleomycin to induce a mouse pulmonary fibrosis model." (PMID 32396525, 2020).
lung fibrosis (continued). "We previously reported that the transcription factor Yin Yang 1 (YY1) is upregulated in fibroblasts treated with TGF-β and in the lungs of mice and patients with pulmonary fibrosis." (PMID 25775215, 2015). "However, it is unclear whether YY1 is an essential mediator of IL-13-induced lung fibrosis." (PMID 25775215, 2015). "In the current study, we demonstrate that PS-NPs trigger an early, compensatory upregulation of FTL in lung epithelial cells, which is transcriptionally regulated by YY1 through its binding to the FTL promoter, thereby promoting ferroptosis and pulmonary fibrosis in vitro and in vivo." (PMID 41560817, 2026). "Although YY1 is traditionally defined as a transcription factor, accumulating evidence indicates that it also contributes to pulmonary fibrosis through additional non-transcriptional mechanisms." (PMID 41560817, 2026). "YY1 is reported to promote the TGF-β-induced EMT and pro-fibrosis in pulmonary fibrosis." (PMID 34818994, 2021). "RT-qPCR and western blot analyses suggested that compared with control mice, mRNA expression of YY1 and HSF1, and expression of miR-214 in the mice with bleomycin-induced pulmonary fibrosis were significantly increased and the expression of THY1 was notably decreased (P < 0.05)." (PMID 32396525, 2020). "Previous studies have demonstrated that YY1 is up-regulated in lung fibroblasts induced by transforming growth factor-β (TGF-β) or tumor necrosis factor-α (TNF-α), both of which are central pro-fibrotic mediators of pulmonary fibrosis." (PMID 32396525, 2020). "Interestingly, increased YY1 expression has also been observed in lung tissues from patients with IPF and murine models of lung fibrosis suggesting its importance in the pathogenesis of IPF." (PMID 32396525, 2020). "Both YY1 and AKT are involved in cell survival as well as in lung fibrosis." (PMID 25775215, 2015). "YY1 showed strong colocalization and marked signal changes with SPC, whereas its overlap with α-SMA was minimal, indicating that YY1 is predominantly upregulated in epithelial cells rather than fibroblasts in PS-NPs-induced pulmonary fibrosis." (PMID 41560817, 2026).
pancreatic ductal adenocarcinoma (10 papers, 2014 to 2024). An infiltrating adenocarcinoma that arises from the epithelial cells of the pancreas. "YY1 can also inhibit the proliferation of pancreatic ductal adenocarcinoma cells by downregulating the expression of its potential target genes." (PMID 35359580, 2022). "As an example, YY1 restrains pancreatic ductal adenocarcinoma cell proliferation and migration through transcriptionally activating CDKN3 expression." (PMID 32943988, 2020). "Tumor suppressor role of YY1 also has been shown in the context of pancreatic ductal adenocarcinoma (PDAC), where YY1 overexpression was found to suppress proliferation, migration, invasion and metastasis of PDAC cells." (PMID 31217904, 2019). "However, YY1 mitigates pancreatic ductal adenocarcinoma metastasis by suppressing MMP10 transcription." (PMID 38351178, 2024). "Additionally, YY1 has been shown to inhibit pancreatic ductal adenocarcinoma progression by suppressing MMP2 expression." (PMID 37724907, 2023). "However, YY1 has been proved to suppressed cell proliferation, migration and invasion in pancreatic ductal adenocarcinoma, indicating that YY1 plays the function as the tumour repressors in gene expression regulation." (PMID 32557953, 2020). "However, its function in cancer remains controversial and the relevance of YY1 to pancreatic ductal adenocarcinoma (PDAC) remains to be clarified." (PMID 24884523, 2014). "Therefore, we presume that YY1 suppresses invasion and metastasis of pancreatic ductal adenocarcinoma by downregulating MMP10 in a MUC4/ErbB2/MEF2C-dependent mechanism." (PMID 24884523, 2014). "It is same with pancreatic ductal adenocarcinoma (PDAC), several reports indicate that YY1 is downregulated in PDAC tissues compared with adjacent normal pancreatic tissues, and the high expression of YY1 represents a better prognosis in patients with PDAC." (PMID 37081988, 2023).
renal fibrosis (10 papers, 2020 to 2025). A final common manifestation of a wide variety of chronic kidney diseases characterized by glomerulosclerosis and tubulointerstitial fibrosis. "Yin Yang 1 (YY1) has been shown to accelerate renal fibrosis in db/db mice by upregulating α-SMA expression and epithelial-mesenchymal transition (EMT)." (PMID 36978091, 2023). "Lately, YY1 was found as a novel target for diabetic nephropathy orchestrated renal fibrosis, suggesting decreasing YY1 expression was beneficial for diabetic nephropathy treatment, which offered us insight for diminish YY1 expression in HCC cells." (PMID 32249890, 2020). "In renal fibrosis, surface decoration with a rabies viral glycoprotein peptide was able to selectively deliver exosomal miR-29 to prevent muscle wastage by inhibiting the transcription factor Yin Yang 1 (YY1)/TGF-β3 axis." (PMID 40676634, 2025). "The overexpression of miR-29a reversed the up-regulation of the transcription factor Yin-Yang-1 (YY1), TGF-β, fibronectin, α-smooth muscle actin, collagen 1A1, and collagen 4A1 and ultimately inhibited renal fibrosis." (PMID 36105281, 2022).
viral infection (10 papers, 2009 to 2025). "We demonstrate that YY1 is required for up-regulating Sox4 expression mediated by HBV and thus, reveal a new role of YY1 in activating Sox4 expression and an association between YY1 expression and viral infection." (PMID 25970172, 2015). "Also, there are several types of the YY1-related diseases, such as viral infection and cancers, which are also linked to abnormal YY1 protein levels." (PMID 19712462, 2009). "The results confirmed the colocalization of ORF3a and YY1 in the macrophage cytoplasm under viral infection." (PMID 40668819, 2025). "In particular, YY1 is known to be involved in viral diseases, playing a role in the activation of HIV-1 replication and in the promotion of oncogenic HPV." (PMID 36851291, 2023). "To determine the impact of YY1 deletion on the expression of translation genes, we sorted viable newly transduced cells on day 3 post‐viral infection." (PMID 35514210, 2022). "Consequently, YY1 plays important roles in a number of biological processes, including cell cycle control, embryogenesis, viral infection, programmed cell death, oncogenesis, Polycomb Group (PcG) function and B-cell development." (PMID 19712462, 2009). "YY1 has been reported to bind to the promoter region of IFN-β in mice and has dual activation and inhibitory effects on IFN-β promoter activity depending on its binding site and time after viral infection." (PMID 38953350, 2024). "To assess the impact of ablating YY1 expression on viral expression, we transfected specific siRNAs into PAMs and found that knockdown of YY1 significantly increased PRRSV ORF7 mRNA levels at 12 and 24 h following viral infection." (PMID 38953350, 2024). "Notably, YY1 could regulate IFN-1 production, contribute to viral gene expression and aid the integration of viral DNA into the host chromosomes during discrete viral infections." (PMID 35658060, 2022).
diabetic nephropathy (9 papers, 2020 to 2025). "In diabetic nephropathy, high glucose conditions induce the upregulation of YY1, promoting the assembly of the mTOR‒YY1 heterodimer." (PMID 41469379, 2025). "Previous studies have reported that the YY1 protein can improve the pathology of diabetic nephropathy by inhibiting the transcription of TGF-β1." (PMID 39519329, 2024). "Emerging evidence indicates that YY1, a multifunctional zinc finger DNA binding transcription factor, is involved in both cancer and kidney disease, including CKD and diabetic nephropathy." (PMID 37507403, 2023). "Although the acetylated transcription factor YY1 participates in EMT, SIRT1 can inhibit EMT in renal tubular cells by inhibiting YY1 acetylation in diabetic nephropathy." (PMID 35484625, 2022).
diffuse large B-cell lymphoma (9 papers, 2014 to 2024). "YY1 is associated with B cell transformation and tumor progression in diffuse large B cell lymphoma (DLBCL), and high levels of YY1 expression are associated with reduced patient survival in DLBCL as well as follicular lymphoma." (PMID 24575094, 2014). "Increased levels of YY1 are correlated with poor survival prognosis in patients with diffuse large B-cell lymphoma (DLBCL), high-grade DLBCL, or Burkitt’s lymphoma, suggesting an oncogenic function of YY1 in human B-cell lymphoma genesis." (PMID 38339244, 2024). "We evaluated the difference in YY1 expression among normal and tumor tissues of lymphoid neoplasm diffuse large B-cell lymphoma (DLBC) and thymoma (THYM) using normal tissues from the genotype-tissue expression (GTEx) dataset as controls (P < 0.01)." (PMID 35791393, 2022). "In another finding, it has been reported that Smurf2 plays a critical role in ubiquitination and degradation of Yin Yang 1 (YY1) in diffuse large B-cell lymphoma cells." (PMID 33722608, 2021). "YY1 expression has also been shown to be highly elevated in Burkitt's lymphoma and diffuse large B-cell lymphoma (DLBCL) as compared to normal cell B cells, and its expression levels links with B-cell transformation and tumor progression." (PMID 31824839, 2019). "In some diffuse large B-cell lymphomas (DLBCL), BCL6 protein expression was positively correlated with the mRNA level of Yin Yang 1 (YY1)." (PMID 25245533, 2014).
follicular lymphoma (9 papers, 2014 to 2023). Follicular lymphoma is a form of non-Hodgkin lymphoma characterized by a proliferation of B cells whose nodular structure of follicular architecture is preserved. "In follicular lymphoma, YY1 appears to act as a tumor suppressor and overexpression of YY1 is associated with favorable outcome with longer survival." (PMID 24674326, 2014). "For YY1, high expression was associated with a worse outcome in hepatoblastoma, DLBCL and follicular lymphoma." (PMID 33315124, 2021). "Similar to another report on lymphoma follicular, we found YY1 expression in a total of 65% of samples (17/26)." (PMID 31040909, 2019). "Compared with reactive lymph nodes, samples from DLBCL and follicular lymphoma (FL), another B-NHL subtype, have significantly higher YY1 transcript levels and an increased YY1 mRNA level has been associated with shorter survival of the patients." (PMID 29564133, 2018). "Further, the oncoprotein PLK1 interacts with and phosphorylates YY1 in follicular lymphoma cells." (PMID 31824839, 2019). "We corroborated our results in cell lines, in a TMA from NHL patients including DLBCL and follicular lymphoma subtypes, in where we analyzed miR-7 by ISH and YY1 and KLF4 using IHC." (PMID 33194748, 2020). "Interestingly, we found that 69% of follicular lymphomas were positive for KLF4, and 65% were positive for YY1, while for DLBCL, KLF4 expression was found in 88% of samples and YY1 expression in 65% of samples." (PMID 31040909, 2019). "The results for follicular lymphoma show that KLF4 vs miR-7 have a negative correlation (r=-0.5229, p=0.0180), and miR-7 vs YY1 also have a negative correlation (r=-0.4248, p=0.0385)." (PMID 33194748, 2020). "Therefore, our results strongly suggest that there is a significant negative correlation between miR-7 expression and that of YY1 or KLF4 in DLBCL and follicular lymphoma." (PMID 33194748, 2020).
leukemia (9 papers, 2014 to 2025). A malignant (clonal) hematologic disorder, involving hematopoietic stem cells and characterized by the presence of primitive or atypical myeloid or lymphoid cells in the bone marrow and the blood. "Therefore, YY1 has been implicated in several hematological malignancies, including leukemia and NHL." (PMID 33194748, 2020). "Specifically, TFs such as YY1, E2F1, and E2F8 were found to be closely associated with m6A activity within leukemia cells." (PMID 38022588, 2023). "Recent studies have shown that YY1 is elevated in patients with non-Hodgkin’s lymphoma and leukemia and its high expression correlates with poor prognosis." (PMID 35163649, 2022). "Yin-Yang transcription factor 1 (YY1) is involved in tumor progression, metastasis and has been shown to be elevated in different cancers, including leukemia." (PMID 35163649, 2022). "Specifically, it was shown that the increased expression of G9a along with the transcription factor YY1 specifically repressed UHRF1 transcription during TPA-mediated leukemia cell differentiation." (PMID 36077796, 2022). "We found that increased expression of G9a along with transcription factor YY1 specifically represses UHRF1 transcription during TPA-mediated leukemia cell differentiation." (PMID 25765655, 2015). "On the other hand, TPA treatment induces leukemia cell differentiation by recruiting YY1 and G9a and represses transcription of UHRF1 via H3K9, a methylation-mediated silencing mechanism." (PMID 25765655, 2015). "Among these regulators, we identified microRNA hsa-miR-548p, whose regulatory relationships with leukemia-related genes including YY1 suggest its novel role in AML pathogenesis." (PMID 25340776, 2014). "In addition, we demonstrated that high nuclear expression of YY1 correlates with poor survival in leukemia patients." (PMID 35163649, 2022). "A well-characterized YY1-miRNA regulatory loop involves miR-200 and miR-15/16, implicated in vascular endothelial growth factor A (VEGFA) regulation in sarcoma and drug resistance in leukaemia." (PMID 27983635, 2016). "The regulatory mechanism underlying YY1 expression in leukemia is still not understood." (PMID 35163649, 2022). "In addition, we recently published that leukemia cell RS4;11 co-expressed both with HIF-1α and YY1 under hypoxia, which correlated with a downregulation of Fas expression." (PMID 35163649, 2022).
nasopharyngeal carcinoma (9 papers, 2018 to 2025). A carcinoma arising from the nasopharyngeal epithelium. "Our review also shortly describes the oncogenic role of YY1 in different cancers such as head and neck squamous cell carcinoma and nasopharyngeal cancer, in which HPV infection is a well-known risk factor." (PMID 35408813, 2022). "For example, NPCCAT1 (a lncRNA) can upregulate YY1 expression, which can further promote the progression of nasopharyngeal carcinoma." (PMID 30965601, 2019). "YY1 can inhibit the transcription of c-Myc by reducing the formation of c-Myc/Max dimers and thereby play an anticancer role via the YY1/c-Myc/miR-141 axis in nasopharyngeal carcinoma." (PMID 33985581, 2021). "Furthermore, we have also recently revealed an additional contribution of YY1 in nasopharyngeal carcinoma (NPC)." (PMID 37081988, 2023). "In nasopharyngeal carcinoma, some scholars have found that NPCCAT1 directly binds to YY1 mRNA 5’UTR, promotes YY1 mRNA translation." (PMID 36626426, 2022).